FOXO3 (forkhead box O3)
Diseases named in the same sentence as FOXO3 in open-access papers (continued):
Sharing a sentence is not in itself a finding about the gene and the disease.
colon carcinoma (continued). "In human colon cancer, markedly reduced FOXO3 levels correlate to advanced tumors." (PMID 35323693, 2022). "However, the nuclear accumulation of FOXO3 and β-catenin promotes malignant progression of colon cancer, suggesting a cell-context dependent role of FOXO3 in tumorigenesis." (PMID 33795838, 2021). "Furthermore, the simultaneous nuclear accumulation of FOXO3 and β-catenin promotes metastasis of colon cancer cells." (PMID 33795838, 2021). "Interestingly, increased FOXO3 activation in cisplatin-resistant colon cancer cells with the small molecule Akt inhibitor, tricirbine/API-2, can override cisplatin resistance by blocking Akt-mediated FOXO3 phosphorylation." (PMID 32372224, 2020). "Moreover, GEN and DAI induce caspase-8 expression and inhibit PI3K activity, which results in an increased level of FOXO3.All these functions lead to a final apoptosis of colon cancer cells." (PMID 29849534, 2018). "Interestingly, increased FOXO3 activation in cisplatin resistant colon cancer cells with a small molecule inhibitor, tricirbine/API-2, can reverse cisplatin resistance by blocking Akt." (PMID 29180117, 2018). "Therefore, our data provide a new clinical insight for treating colon cancers by regulating FOXO3 with REP1, a novel oncogenic protein." (PMID 28055019, 2017). "In this respect, FOXO3 promotes cancer stem cell survival, metastasis in colon cancer and drug resistance, suggesting that tumor cells may “learn” under certain micro-environmental circumstances to exploit the “longevity talent” of FOXO3." (PMID 27769056, 2016). "However, this phenomenon can be regarded as a sort of vulnerability exploited to restore FoxO signaling with inhibitors of nuclear export, as shown for FoxO1 with the XPO1 inhibitor selinexor in combination with cisplatin in ovarian cancer cells or for FOXO3 with psammaplysene in colon cancer cells." (PMID 30646603, 2019). "HCT-116 5FUR cells display downregulation of FOXO3 and increased expression of FOXM1 compared to parental colon cancer cell lines." (PMID 35910798, 2022). "Moreover, relatively high co-expression scores were also observed for RUNX2/ETS1, RUNX2/FOXO3, HNF1B/HNF4A, and HNF1B/FOXA3, suggesting that the DETFs associated with DARs might work together and be responsible for 5-FU resistance in colon cancer cells." (PMID 35252200, 2022). "This is consistent with studies showing that the forkhead TFs FOXO3 and FOXA1, which have a 2 and 2.4-fold increase in gainability in colon/rectum cancer respectively, promote colon cancer proliferation." (PMID 33077858, 2020). "Hydroxytyrosol promoted ROS production, which activated the PI3K/AKT/FOXO3 pathway with subsequent regulation of FOXO3 targets, including catalase and SOD, resulting in the induction of apoptosis in DLD1 colon cancer cells and a reduction in cellular antioxidant defenses." (PMID 40979569, 2025). "Furthermore, consistent with the fact that the miR-183/96/182 cluster directly targets SMAD4 and FOXO3, they observed a significant increase in the levels of SMAD4 and FOXO3 following avenanthramide C treatment in colon cancer cells." (PMID 39334758, 2024).
colon carcinoma (continued). "Genistein reduced the proliferation of colon cancer cells by diminishing the negative impact of epidermal growth factor (EGF) on the activity of FOXO3." (PMID 39334758, 2024). "In addition to PDCD4, AR inhibition also upregulated phosphatase and tensin homolog (PTEN), another miR-21 target, as well as forkhead box O3A (FOXO3a) in HT29, SW480, and Caco-2 colon cancer cells." (PMID 39055885, 2024). "We found that FOXO3 was a significantly protective factor in disease-specific survival (DSS), overall survival (OS), and progression-free survival (PFS) for kidney clear cell carcinoma (KIRC), uveal melanoma (UVM), and colon cancer (COAD)." (PMID 36555288, 2022). "Additionally, we established the significance of the macrophage-FOXO3 axis in both IBD and colon cancer." (PMID 35323693, 2022). "Whilst the interaction between FANCD2 and FOXO3 has not been directly linked to cancer metastasis, FANCD2 overexpression on its own has been shown to be correlated with lymph node metastasis of colon cancer." (PMID 32372224, 2020). "Active FOXO3 attenuates proliferation by upregulation of the cell cycle inhibitor p27kip1, and we showed that EGF-induced FOXO3 disassociation from the p27kip1 promoter is inhibited by genistein in colon cancer cells." (PMID 21639915, 2011). "It was found that FoxO3 overexpression increased the sensitivity of colon cancer cells SW620 and HCT-8 to 5-FU and that the reversal of resistance of human colorectal cancer cells to 5-FU was demonstrated through the involvement of FoxO3 in the inhibition of the Nrf2/TR1 signaling pathway." (PMID 37359553, 2023). "Moreover, we demonstrated that in PMNs, a negative regulatory network of LDs and FOXO3 might be one of the mechanisms of colonic inflammation and tumorigenesis within IBD and colon cancer." (PMID 37298680, 2023). "Additionally, we identified a specific transcriptional signature for the macrophage-FOXO3 axis (MAC-FOXO382), which separated the transcriptome of affected tissue from control in both IBD (p = 5.2 × 10−8 and colon cancer (p = 1.9 × 10−11), revealing its significance in human colonic pathobiologies." (PMID 35323693, 2022). "Notably, Foxo3 upregulation has not been specifically observed in colon cancer cells treated with butyrate, although Foxo3 expression does modulate a number of pro-apoptotic genes associated with butyrate’s antineoplastic effects." (PMID 34359944, 2021). "We hypothesize that anti-proliferative properties of genistein in colon cancer cells are mediated by inhibition of the negative effect of EGF on FOXO3 activity, thus promoting cell cycle arrest." (PMID 21639915, 2011). "Moreover, the high basal level of phosphorylated FOXO3 (inactive) in sub-confluent HT-29 cells was significantly diminished by genistein, further supporting that genistein promotes FOXO3 activity in proliferative colon cancer cells regardless of EGF stimulation." (PMID 21639915, 2011). "All of these data led us to the conclusion that siREP1-mediated cell death was alleviated by inhibition of FOXO3, that is, REP1 could function in cell survival under various stress conditions by conferring negative effects to FOXO3-dependent apoptosis in colon cancer cells." (PMID 28055019, 2017).
lung cancer (80 papers, 2010 to 2025). A malignant neoplasm involving the lung. "The miR-155 has also been associated with circular RNA FOXO3 (circ-FOXO3) and FOXO3 in lung cancer migration and invasion." (PMID 32372224, 2020). "However, Sp1 downregulation in the late stages of lung cancer leads to a decrease in miR-182 expression, causing FOXO3-mediated tumor metastasis by increasing the expression of N-cadherin, ADAM9, CDH9, and CD44." (PMID 37438760, 2023). "We conclude from our study that blood DNA methylation at FOXO3 might be associated with gastric and lung cancer survival." (PMID 34943892, 2021). "The intensification of SIRT1’s deacetylating activity in lung cancer cell lines A549 and H1435 leads to the deacetylation of the FOXO3 (forkhead box O3) factor and its increased susceptibility to ubiquitination and proteasomal degradation." (PMID 37762053, 2023). "The downregulation of miR-96 upregulated SAMD9 which accelerates the action of cisplatin and suppresses lung cancer progression by regulating forkhead box O3 (FOXO3)." (PMID 36778005, 2023). "Our previous studies have indicated that Sp1-mediated miR-182 expression silences FOXO3 to enhance lung cancer malignancy." (PMID 35034634, 2022). "Taken together, SIRT3 elevation inhibits cisplatin resistance of lung cancer cells through FOXO3/CDT1 axis in vivo." (PMID 33655712, 2021). "Coherently, FOXO3 promoted cisplatin resistance to lung cancer cells, which was reversed by CDT1 elevation." (PMID 33655712, 2021). "In fact, cross-talks between miR-155-5p and FOXO3 have been shown to modulate cell growth in lung cancer." (PMID 32372224, 2020). "In vitro and in vivo lung cancer studies have revealed the contribution of miR-155 in a resistant phenotype by targeting Forkhead Box O3 (FOXO3A) and in an improvement of CSC properties." (PMID 31137686, 2019). "We have showed that BBR inhibited growth of non‐small cell lung cancer (NSCLC) cells through mitogen‐activated protein kinase (MAPK)‐mediated increase in forkhead box O3a (FOXO3a)." (PMID 28840963, 2018). "Shikonin induced apoptosis of lung cancer cells via activation of Forkhead box O3 (FOXO3a)/early growth response protein 1 (EGR1)/Sirtuin 1 (SIRT1) signaling antagonized by p300." (PMID 30420490, 2018). "In conclusion, in the early stages of lung cancer progression, Sp1 stimulates miR-182 expression, which in turn decreases FOXO3 expression." (PMID 24519909, 2014). "We identified a novel Sp1-regulated miRNA, miR-182, in lung cancer cells and demonstrated that Sp1 downregulated FOXO3 expression by upregulating miR-182 expression." (PMID 24519909, 2014). "The levels of FOXO3 and Sp1 in the lung cancer cell lines, A549, H1299, CL 1-0, and CL 1-5, were studied." (PMID 24519909, 2014). "The effects of miR-182 knockdown were partially reversed by knockdown of FOXO3, suggesting that miR-182 functions as a suppressor of lung cancer metastasis by repressing FOXO3 expression." (PMID 24519909, 2014). "Shikonin induced apoptosis in lung cancer cells through the activation of FOXO3." (PMID 39334758, 2024). "Moreover, FOXO3 represses the DNA methyltransferase 3B (DNMT3B) by interacting with a binding site within the DNMT3B promotor in human lung cancer cell lines (A549 and CL1-5) in vitro." (PMID 38132107, 2023). "In addition, an increasing number of studies have indicated that FOXO3 is a tumor suppressor in many cancers, including gastric, colorectal, breast, and lung cancers." (PMID 37667288, 2023).
lung cancer (continued). "Sp1 transcription factor, a member of a specificity protein / Krüppel-like family, positively regulates miR-182 expression, which in turn inhibits FOXO3 translational activity and subsequently promotes the growth of cancer cells n the early stages of lung cancer progression." (PMID 37438760, 2023). "One study found that EVs derived from human umbilical cord mesenchymal stem cells (hUCMSCs-EVs) could transfer miR-130b-3p into lung cancer cells and promote the occurrence and development of lung cancer through the FOXO3/NFE2L2/TXNRD1 axis." (PMID 35860555, 2022). "As expected, Myc‐CDT1 were interacted with Flag‐FOXO3 in lung cancer cells." (PMID 33655712, 2021). "In subsequent analysis, to elucidate whether FOXO3/CDT1 axis was related to resistance of cisplatin to lung cancer, FOX3 was downregulated and upregulated in A549 cells, and then, treated with cisplatin." (PMID 33655712, 2021). "Moreover, we obtained translational IHC data by using a tissue microarray prepared from samples of lung-cancer patients, and the results indicated that the expression of FOXO3 and RRM2B can be used as a predictive biomarker in future cancer diagnostics." (PMID 24947616, 2014). "The expression of Sp1 and FOXO3 in patients with lung cancer was examined." (PMID 24519909, 2014). "However, depletion of miR-182 was sufficient to impair the Sp1-mediated reduction of FOXO3 expression in our experiments, suggesting that miR-182 is the major regulator of FOXO3 in lung cancer cells." (PMID 24519909, 2014). "However, downregulation of FOXO3 promoted DNMT3B overexpression, leading to tumor growth in lung cancer, while clinical findings also showed that there was a high DNMT3B, low FOXO3a, and high MDM2 expression associated with low survival rates in lung cancer patients." (PMID 35847844, 2022). "The same working group also revealed that in lung cancer patients, lower levels of FOXO3 and higher levels of DNMT3B were correlated with a poor prognosis for lung cancer." (PMID 38132107, 2023). "In lung cancer, several reports have recognized miR-498-5p as a tumour suppressor by targeting HMGA2, tripartite motif containing 44 (TRIM44) or forkhead box O3 (FOXO3)." (PMID 37667197, 2023). "Taken together, SIRT3 regulates FOXO3/CDT1 axis, thus enhancing cisplatin resistance of lung cancer cells." (PMID 33655712, 2021). "The elevation of SIRT3, FOXO3, or CDT1 inhibited cell cisplatin resistance of lung cancer cells as well as inhibited viability, proliferation, and invasion in vitro." (PMID 33655712, 2021). "The expression patterns of SIRT3, FOXO3, and CDT1 were determined using RT‐qPCR and Immunoblotting in lung cancer." (PMID 33655712, 2021). "In subsequent experiments, we found that FOXO3 positively regulated CDT1 expression, and its elevation inhibited cell cisplatin resistance of lung cancer cells as well as inhibited viability, proliferation." (PMID 33655712, 2021). "CDDP sensitivity is suppressed partly by circAKT3 by modulating the miR-516b-5p/STAT3 axis in lung cancer cells, whereas CDDP sensitivity is promoted by circRNA-FOXO3 via the miR-543/Foxo3 axis in NSCLC cells." (PMID 35070998, 2021). "The cancer tissue microarray data also demonstrated a strong correlation between the co-expression of FOXO3 plus RRM2B and increased disease survival and reduced recurrence or metastasis in lung cancer patients." (PMID 24947616, 2014). "SIRT3, FOXO3, and CDT1 expression was suppressed in the lung cancer tissues and cells." (PMID 33655712, 2021). "Furthermore, FOXO3 upregulates miR-622 to suppress hypoxia-inducible factor 1 alpha (HIF-1α) to induce cell invasion and migration in lung cancer." (PMID 32372224, 2020). "A number of studies have documented curcumin mediated anti-proliferative effect in lung cancer cells via modulation of various molecular targets such as STAT-3, EGFR, Forkhead Box O3 (FOXO3a), Eukaryotic Initiation Factors (eIFs), and Transforming Growth Factor-Beta (TGF-β)." (PMID 31817718, 2019).
lung cancer (continued). "In lung cancers, AMPK may employ distinct methods to affect the transcriptional ability of FOXO3." (PMID 39456981, 2024). "To further confirm whether FOXO3 is regulated by SIRT3 at acetylated level, we adopted Immunoblotting displayed that compared with normal lung cells, reduced level of SIRT3 and increased ace‐FOXO3 level were observed in lung cancer cells." (PMID 33655712, 2021). "Moreover, a JNK-mediated up-regulation of FoxO1, FoxO3 and FoxO4 regulating the transcription of the downstream target BIM, critical for apoptosis induction by the EGFR inhibitor AG1478, has been reported in PC-9 lung cancer cells." (PMID 30646603, 2019). "Although we found that FOXO3 is involved in miR-182-mediated lung cancer progression, FOXO3 knockdown did not completely abolish the effects of miR-182 knockdown, suggesting that other genes regulated by miR-182 contribute to the inhibition of metastasis by miR-182." (PMID 24519909, 2014).